ARG1 (arginase 1)
Diseases named in the same sentence as ARG1 in open-access papers (continued):
Sharing a sentence is not in itself a finding about the gene and the disease.
tumor (continued). "Additionally, the expression of M1 macrophage markers CD86 and CD80 in tumor tissues surpassed that in adjacent tissues, while the expression of M2 macrophage markers CD163, CD206, and Arg-1 in tumor tissues was also higher than in adjacent tissues (p<0.05, p<0.01)." (PMID 39531417, 2024). "RNA-Seq of bulk tumor samples verified an enrichment of neutrophil-derived genes in combination-treated tumors, specifically, genes associated with pathological activation of neutrophils and MDSC-mediated suppressive function, such as S100a8/a9, Mmp9, and Arg1." (PMID 37988164, 2024). "Importantly, since the release of ARG1 occurs upon tumor infiltration, arginine levels in the TME may be even further reduced." (PMID 39211039, 2024). "Interestingly, the combination treatment of Eto and IKE blocked MDSCs’ immunosuppressive function and accumulation by downregulating the expression of SLC7A11, GPX4, and ARG1 while promoting T-cell proliferation and infiltration into tumor tissues to enhance cancer therapy." (PMID 39596904, 2024). "Therefore, upregulation of STAT3, ARG1 and IDO in TME of KRASmut tumors in our results might be due to the infiltration of tumor-associated macrophages and tumor-associated neutrophils in TME." (PMID 36831441, 2023). "However, arginine increased in the HCC group, which might be attributed to the suppression of the arginine-degrading enzyme arginase I (ARG1), and arginine was also reported to promote tumour growth." (PMID 36599851, 2023). "Thus, an increased ARG1 expression is a key factor for the rapid growth and deterioration of tumor." (PMID 38012650, 2023). "The consequences of this communication mechanism are two-fold: tumors can remove Arg-1 from the primary microenvironment using exosomes to (a) induce systemic immune suppression and (b) prepare distant lymph nodes for metastasis, thereby promoting tumor growth and the development of recurrence." (PMID 38001706, 2023). "In addition, upregulation of ARG1, iNOS and CD206 expression induced by CM from GL261 cells was impaired in Ana-1-KO cells, suggesting a role for Siglec-15 in regulating the polarization of tumor-associated macrophages." (PMID 37234161, 2023). "An increasing number of studies have shown that arginase 1 and 2 play a key role in the regulation of tumour growth and metastasis through various mechanisms, including the regulation of L-arginine metabolism, the modulation of signalling pathways, and influencing the tumour microenvironment." (PMID 37446252, 2023). "Then, some ARG1-positive cells may leave the tumour and migrate to the lungs." (PMID 37980483, 2023). "In addition, ARG1 mediated tumor escape to promote rapid tumor growth." (PMID 38012650, 2023). "Furthermore, compared to the tumor-bearing control, cryo-thermal therapy upregulated the expression of both stimulatory cytokines and suppressive molecules in MDSCs, except for unchanged levels of Arg-1 and IL-12 and downregulation of iNOS." (PMID 37108179, 2023). "Although neither of the 2 stimuli alone could fully induce the expression of Arg1, we found a strong synergistic effect, suggesting that heme, in conjunction with factors provided by the tumor cell culture supernatant, serves as a potent signal for the generation of heme-TAMs." (PMID 38060331, 2023). "Moreover, upon SKI-II treatment, we observed a significant downregulation of Arg1 expression in the RAW264.7 cells co-cultured with all the tumor cell lines tested, accompanied by increased gene expression of the M1 marker Tnfα and IL-6 cytokine level in the cell-free supernatant of RAW264.7 cells." (PMID 36672428, 2023). "These correlation analyses further supported that MHC-II+/BST2+ Macrophages, CD43−IgD+ mature B cells, and cDCs might contribute to anti-tumor immunity, whereas Arg-1+ Macrophages, CD43+IgD− immature B cells, MDSCs, and Tregs may have immunosuppressive effects in PDAC." (PMID 35316682, 2022).
tumor (continued). "The high production of arginase-1 (Arg-1) by MDSCs causes L-arginine deficiency in the tumor microenvironment, which either provokes the cell cycle arrest to the G0–G1 phase of T cells and the downregulation of TCR expression, inducing T cell dysfunction and tumor escape in vivo." (PMID 35757002, 2022). "Furthermore, scientists observed a higher amount of M2-associated mRNAs for e.g., IL-10, Arg-1, and TGFβ and the reduction of M1-associated mRNAs such as TNF-α, IL-6, and IL-12 in tumor-associated macrophages from EC specimens, in comparison to macrophages obtained from healthy specimens." (PMID 35563789, 2022). "However, in this study we found the deficiency of Arg1 in macrophages did not affect T cells cytokine production in the lung microenvironment of B16 tumor-bearing mice." (PMID 35778404, 2022). "In addition, flow cytometry and immunofluorescent analysis of tumor samples demonstrated a significant reduction in the percentage of CD4+ T cells along with Arginase-1+ cells/macrophages in the tumors in the combination treatment arm than in the nivolumab-alone arm." (PMID 36212401, 2022). "Furthermore, Maf, Atf3, and Hif1a are potential regulators of regulatory myeloid (Mreg) cells, while Hif1a is a potential regulator of tumor-associated macrophages in MCA205 mouse tumors; these two myeloid subpopulations share the expression of Arg1 and Trem2 (Arg1+Trem2+)." (PMID 35359989, 2022). "Additionally, a positive correlation has been observed between ARG1 expression and histone Kla levels, but not histone Kac levels in tumor-associated macrophages (TAMs)." (PMID 35224683, 2022). "Moreover, IL-9 promoted Arg1 expression from IMs isolated from tumor bearing mice ex vivo." (PMID 35778404, 2022). "Although some canonical markers such as iNOS and ARG‐1 may represent the two extremes of the M1 and M2 polarization states, macrophages with intermediate polarization and different activation markers often coexist in tumours." (PMID 35656866, 2022). "Indeed losses in CD3ζ chain expression in peripheral blood lymphocytes have been reported in patients under conditions that might lead to Arg1 activation, including tumor growth, overwhelming infections and trauma." (PMID 35887950, 2022). "Thus, CA may reduce the immunosuppressive activity of arginase 1 in macrophages of the spleen and the peritoneal cavity and prevent inhibition of NO-mediated cytotoxicity in tumor cells." (PMID 36142391, 2022). "Inspection of these markers in regions of elevated CD73 showed that HIF1A, GLUT1, and ARG1 were enriched in tumor cells adjacent to regions of palisading necrosis, again suggesting that hypoxia may promote the expression of CD73 in neighborhoods that drive immunomodulatory signaling." (PMID 35973991, 2022). "Finally, we isolated the CD15+ cells and CD4/CD8pos T cells at 24 h from APCCs and analyzed the expression of key immune‐suppressive genes of MDSCs (ARG1, NCF1, NCF4, CYBB) which mediate MDSC arginase 1 secretion and NO generation to inhibit T cells within the tumor TME." (PMID 35611994, 2022). "Therefore, M2 macrophages secrete ARG-1 to promote tumor growth and angiogenesis." (PMID 35889289, 2022). "Recent studies have confirmed that ARG1 can be induced in alternately activated (M2) macrophages and is involved in the occurrence and development of tumors, mainly due to the anti-inflammatory response, tumor immunity, tumor proliferation, metastasis, and immunosuppression." (PMID 36212404, 2022). "Therefore, altered expression of ARG1 may lead to changes in the metabolism of the liver tissue and have marked effects on the metabolic and growth statuses of tumor cells." (PMID 36212404, 2022). "Another study showed that combination treatment of GLS inhibitors with ICIs significantly decreased tumor volume in an ICI-resistant-tumor mouse model, and the possible underlying mechanism may via enhancing CD8+ T cell activities and by decreasing ARG1-expressing myeloid cells." (PMID 33514004, 2021).
tumor (continued). "Importantly, pre-treatment of B16 cells with Hsp70-bearing EVs resulted in a decline of arginase-1-positive macrophages, showing no generation of tumor-associated macrophages." (PMID 34716378, 2021). "Therefore, Arg-1 may affect the prognosis of ICC patients through the regulation of tumor immune microenvironment, which plays an important role in the development of ICC." (PMID 34715880, 2021). "They further concluded that this might be of significant biological relevance, listing confirmatory studies describing the reciprocal regulation of iNOS and ARG1 expression in macrophages during tumour rejection and progressive tumour growth as well as in wound healing." (PMID 33460504, 2021). "Similarly, targeting the immunosuppressive enzyme arginase 1 (ARG1), could also improve anti-tumor immune responses." (PMID 33747948, 2021). "Therefore, miR-155 downregulation along with Arg1 upregulation observed in M1-like macrophages differentiated with MN/MCA CM might represent an advantage for tumor promotion." (PMID 34680504, 2021). "Similarly, a massive accumulation of CD206+ or ARG1+ macrophages has also been found in an inflammation‐mediated skin tumorigenesis mice model, while macrophage ablation has been shown to significantly reduce tumor incidence." (PMID 33463063, 2021). "Interestingly, the resulting alternatively activated macrophage population is characterized by expression of markers (Ym1, Fizz1, Arg1) that previously have been attributed to a subset of pancreatic macrophages (usually described as Ym1+ macrophages) that drive fibrinogenesis and tumor progression." (PMID 34328416, 2021). "PDE5 inhibitors such as sildenafil and tadalafil could affect MDSCs functions by decreasing the expression of arginase 1 (ARG1), IL4Ra, and the concentration of reactive oxygen species (ROS), which would increase the cytotoxic activity of NK cells against tumor cells." (PMID 33718200, 2021). "Importantly, we found that myeloid cells from MCA203-W30L tumor-bearing mice expressed lower level of both ARG1 and NOS2 enzymes as compared to the control, that could potentially explain their reduced suppressive activity." (PMID 34675917, 2021). "However, also high expression of arginase 1 (Arg1) in TAMs could contribute to low arginine concentrations, which is required for T cell survival and anti-tumor responses." (PMID 33171762, 2020). "Hence, we tested the expression of iNOS and Arg-1 in PBMCs after co-cultures with OSCC, and found OSCC could enhance the levels of iNOS and Arg-1, providing evidence that tumor cells could educate the immune cells to immunosuppressive phenotype." (PMID 32092078, 2020). "Blockade of arginase-1 using a small molecule inhibitor did reverse the myeloid cell-mediated suppression of T-cell activity and proliferation and did reduce the growth of melanoma, lung cancer and breast tumors in vivo due to increased NK and T-cell infiltration into the tumor microenvironment." (PMID 32604862, 2020). "Therefore, alkaline pH values close to the Arginase-1 optimum as well as more neutral pH values may both be relevant for Arginase-1 functioning inside a tumor." (PMID 32647818, 2020). "Furthermore, neutrophils are able to sustain tumor progression through the release of proangiogenic factors such as VEGF and MMP9 and, by maintaining an immunosuppressive tumor microenvironment through the expression of the arginine-consuming enzyme Arg1 and ROS production." (PMID 32580431, 2020). "Therefore, all these data suggest that a partial blockade of PDIA3 in T98G cells might attenuate the pro-tumor microglia activation since it tends to reduce the M2 parameters (urea and ARG1) and IL6 release by microglia." (PMID 33153019, 2020). "In tumors, Arginase-1 may therefore function at alkaline pH during the early phase of phagocytosis, while it may continue to function at more neutral pH values in the later stages of phagosome maturation and in the extracellular tumor microenvironment." (PMID 32647818, 2020).
tumor (continued). "Furthermore, RNA-seq analysis showed that TAMs from Mye-Tet2 null mice overexpressed genes associated with the M1 pro-inflammatory signature, while typical genes of M2 immunosuppressive macrophages, among which Arg-1, were down-modulated, compared to TAMs from wild-type tumor-bearing mice." (PMID 33212945, 2020). "In vitro treatment of macrophage cell lines with a P2Y12 antagonist increased tumor cell phagocytosis and increased the expression of the anti-tumoral macrophage marker HLA-DR, while simultaneously reducing the expression of the pro-tumoral macrophage marker arginase-1." (PMID 33142937, 2020). "Finally, these results were corroborated using mice deficient in Arginase 1 expression in Tie2 positive cells demonstrating that the anti-tumor efficacy of the PD-1 blockade was not improved when arginase 1 was absent." (PMID 31481761, 2019). "Therefore, a combined targeting of ARG1 and IDO1 using pharmacological compounds could be an effective treatment to constrain tumor-associated immunosuppression improving cancer immunotherapy." (PMID 31447834, 2019). "Therefore, we hypothesized that ARG1 can be released from tumor cells in EVs and found ARG1+ small EVs in ascites, as well as in the plasma of OvCa patients." (PMID 31278254, 2019). "Finally, IL‐35 is emerging as an important target in tumour immunotherapy because of its inactivation could lead to the inhibition of Arg1, one of the most important immune checkpoints allowing tumour immune escape." (PMID 30793469, 2019). "We identify hereby a novel mechanism of tumor-induced systemic T-cell dysfunction based on the activity of tumor-derived ARG1+ EVs, that may also apply to other arginase-expressing tumor types and may have significant clinical implications for T-cell immunotherapy approaches." (PMID 31278254, 2019). "Notably, circulating monocytes may acquire both ARG1 expression and MDSC-associated functions after tumor-derived exosomes uptake suggesting exosomes as tumor-derived cues to reprogram monocytes into immunosuppressive cells." (PMID 31533831, 2019). "Notably, patients who did not respond to treatment had higher circulating neutrophil and ARG1 levels in the tumour microenvironment at the time of Tru-cut biopsy, supporting greater immune suppression by trastuzumab, which is one explanation for its missed activity." (PMID 30478407, 2018). "Notably, the expression of miR-494 in MDSCs downregulates the protein levels of PTEN, increases the activity of the AKT pathway, and upregulates ARG1 and iNOS, thus contributing to the accumulation of MDSCs in the tumor tissue and promoting tumor cell invasion and metastasis." (PMID 30443251, 2018). "Thus, abolishment of ARG-1 expression in TAMs, reduced the M2 response and impeded the production of polyamines, which are necessary not only for tumor cell proliferation, but also for tumor cell invasion and metastasis." (PMID 30138430, 2018). "Compared with C-MOs, MAMPCs expressed higher levels of TAM signature genes (i.e., Arg1, Cdh1, Hmox1, Il1r2, Mrc1, and Stab1) that were also highly expressed by MAMs, suggesting that differentiation of C-MOs to MAMPCs (M-MDSCs) is directed toward the tumor-promoting macrophages." (PMID 29387063, 2017). "Tumor-derived lactate is up-taken by tumor-associated macrophages (TAMs) through their MCTs active transporters on the cell membrane, leading to the transcription of the vascular endothelial growth factor (VEGF) and the l-arginine-metabolizing enzyme arginase-1 (ARG1) genes." (PMID 26909082, 2016). "However, since PMNs isolated from healthy dogs did not express detectable ARG-1 mRNA or impair T cell function, suggesting that ARG-1 may be a tumor-induced mechanism that MDSCs could employ for T cell suppression." (PMID 22428007, 2012).
tumor (continued). "Future investigations should characterize macrophage subsets (such as iNOS/CD86 versus Arg1/CD206) using flow cytometry or multiplex immunostaining to determine whether macrophage-derived cytokines contribute to IL-6/STAT3 signaling during UVB-driven tumor promotion." (PMID 41596287, 2026). "Several ARG1 inhibitors, such as OATD‐02 and CB‐1158, have recently been selected for clinical trials in tumour immunotherapy." (PMID 41503514, 2026). "Related to this, we found that there are high levels of myeloid cell infiltration early in mBT0309 tumor development and that IGF2KD led to decreased ARG1+ myeloid cells in the TME." (PMID 41568176, 2026). "Examination of infiltrating M-MDSCs showed reduced expression of arginase 1 and inducible nitric oxide synthase 2 (iNOS2) (immunosuppressive markers) in Pgdfl/flLysMCre compared to Pgdfl/fl AT3 tumor models." (PMID 41535266, 2026). "Both tumor-promoting CD206+MHCII+/− and CD206−MHCII+ inflammatory macrophages were increased in tumors, and TAMs showed higher ARG1 expression." (PMID 40588561, 2025). "In HCC, neutrophils contribute to tumor progression through IL-6 and TNF-α-mediated inflammation, promoting angiogenesis and immune suppression via mechanisms involving arginase-1 and ROS." (PMID 40387965, 2025). "IHC analysis further confirmed an M2‐biased tumour microenvironment, showing increased expression of CD206 and Arg‐1 alongside decreased CD86 and iNOS expression in LDHA‐overexpressing tumours." (PMID 41399129, 2025). "In primary tumor tissue, infiltrating CD4+ T cells negatively correlated with Apo-A1 protein level and arginase-1 expression in infiltrating neutrophils." (PMID 40358184, 2025). "Specimen staining showed single-cell tumor cells positive for CK7 > CK20; there was very weak and patchy positivity for HepPar1, and negativity for Arginase-1." (PMID 40426891, 2025). "These cells contribute to the formation of an immunosuppressive tumor microenvironment and promote tumor progression by producing MMP9 and ARG1." (PMID 40740234, 2025). "These M2 macrophages secrete anti-inflammatory cytokines and express markers like arginase-1 (ARG1), mannose receptor (CD206), and IL-10, which facilitate tissue remodeling, angiogenesis, and tumor immune evasion." (PMID 39949765, 2025). "In contrast, the expression levels of MPO, ELA2, ARG1, and ICAM1 remained unchanged in all treatment groups, indicating that rhGDF15 and rhTNF-α have selective effects on tumor-promoting cytokine expression." (PMID 41035818, 2025). "Neutrophils contribute to the establishment of pre-metastatic niches by secreting chemokines such as ARG1, CXCL1, CXCL2, CXCL10, CCL2, CXCR2, and vascular endothelial growth factor A (VEGFA), which attract tumor cells to metastatic sites." (PMID 40227814, 2025). "The combination treatment and reduction of immunosuppressive markers such as Arginase 1 and CD206 indicated a shift toward a more immune-permissive tumor microenvironment." (PMID 40684232, 2025). "Combining ARG1 inhibition with RT reduced TAN infiltration, restored CD8+ T cell presence, and delayed tumor growth." (PMID 40805288, 2025). "The Arginase 1-positive Orthochromatic erythroblasts might hold significant importance in evaluating different immunosuppressive microenvironments aside from the normal bone marrow microenvironment, such as the extramedullary erythropoiesis microenvironment or the tumor microenvironment." (PMID 40427045, 2025). "With these carboxylic acid-modified derivatives in hand, we investigated their impact at 10 μM on ARG1 and NOS2 mRNA expression in RAW 264.7 cells pre-stimulated with IL-4/IL-13 to evaluate the effects on the pro-tumor phenotype of macrophages." (PMID 40430260, 2025). "Compared with those of HH, the ARG1, CPS1, HNF4α, and HNF1α expression levels in tumor cell lines are minimal, if at all." (PMID 40963742, 2025).